CD247 (CD247 molecule)
Diseases named in the same sentence as CD247 in open-access papers (continued):
Sharing a sentence is not in itself a finding about the gene and the disease.
melanoma (6 papers, 2018 to 2025). A malignant, usually aggressive tumor composed of atypical, neoplastic melanocytes. "Our results suggested that TNF receptors, MHC molecules, ITGAM, CD247 or CD14 leading gene sets can preciously distinguish the responders for non-responders in patients with melanoma that received ICB therapies." (PMID 34238310, 2021). "CD14, ITGAM, CD247 and MHC molecules not only significantly dysregulated between the responders and non-responders of patients with melanoma but also presented accuracy prediction of immunotherapy response." (PMID 34238310, 2021).
rheumatoid arthritis (5 papers, 2012 to 2022). A chronic, systemic autoimmune disorder characterized by inflammation in the synovial membranes and articular surfaces. "TCRA rs6572493 has not yet been associated with any health risks, but CD247 rs2995082 has been associated with celiac disease and rheumatoid arthritis." (PMID 26872611, 2016).
Allergy (3 papers, 2009 to 2025). An allergy is an immune response or reaction to substances that are usually not harmful. "Some of these genes have a known function that is relevant to allergic disease, including F11R, CD247, PGAP3, AAGAB, CAMK4 and PEX14, and so could be prioritized for functional follow-up." (PMID 29333270, 2017).
asthma (3 papers, 2020 to 2024). "The SIgAD signal in CD247 appeared to have been modulated by the cFDR procedure due to our conditioning on asthma, with which this SNP is significantly associated." (PMID 39241920, 2024). "Expression levels of BACH2 (P = <0.0001 for both) and CD247 (P = 0.0002, vs. C and P = 0.0204 vs. MA for CD247) were significantly lower in severe asthma compared to controls and mild-moderate asthma." (PMID 35386986, 2021). "Additionally, I found that CD2AP, which is highly interacted with CD247 is highly correlated with moderate-to-severe asthma." (PMID 32512817, 2020). "They concluded that certain SNP occurrences in genes such as CD247, ERBB2, IL1RL1 and several interleukin family genes are strongly correlated with moderate-to-severe asthma." (PMID 32512817, 2020). "Although studies in asthma are lacking, type 2 (non-insulin dependent) diabetics have shown chronic inflammation resulted in immunosuppression and CD247 downregulation." (PMID 35386986, 2021).
breast carcinoma (3 papers, 2016 to 2025). "CDK12 can promote the occurrence of HER2-positive breast cancer by promoting the expression of cathepsin E, and DHRS9 and CD247 can protect against HER2-positive breast cancer by reducing cathepsin E expression." (PMID 39944834, 2025). "Cathepsin E can mediate the effects of APBB1IP, NT5C3B, and ZNF66 on HER2-negative breast cancer, as well as the effects of DHRS9, CDK12, and CD247 on HER2-positive breast cancer." (PMID 39944834, 2025).
cholangiocarcinoma (3 papers, 2021 to 2023). A carcinoma that arises from the intrahepatic biliary tree (intrahepatic cholangiocarcinoma) or from the junction, or adjacent to the junction, of the right and left hepatic ducts (hilar cholangiocarcinoma). "Three tumor antigens, such as CD247, FCGR1A, and TRRAP, correlated with superior prognoses and infiltration of antigen-presenting cells were identified in cholangiocarcinoma." (PMID 33685460, 2021). "CD247, FCGR1A, and TRRAP are potential antigens for mRNA vaccine development against cholangiocarcinoma, specifically for patients with IS2 tumors." (PMID 33685460, 2021).
COVID-19 (3 papers, 2021 to 2024). A disease caused by infection with severe acute respiratory syndrome coronavirus 2. "Increased expression of CD3E and a suppression of CD3ζ (CD247) was observed on MAIT and γδT cells in COVID-19 samples." (PMID 34721400, 2021).
diabetes (3 papers, 2015 to 2022). "Moreover, Cd247 (CD3 zeta chain) was identified as a novel diabetes susceptibility gene whose function positively influenced the onset of autoimmune diabetes in mice when the gene was disturbed during TCR signaling." (PMID 26606254, 2015). "It has been suggested that the expression levels of CD247 may be a sensitive and predictive biomarker of chronic inflammation in diabetes." (PMID 35184642, 2022). "CD247 and LCK have both been previously linked to diabetes and which could warrant further investigation." (PMID 33933144, 2021).
lung carcinoma (3 papers, 2017 to 2022). "Previous studies have shown that CD3D may serve as a prognostic maker of colon cancer, gastric cancer and other tumors; CD3E can be used as a prognostic factor of lung cancer; the expression of CD247 was associated with many cancers, including gastric cancer, head and neck cancer and ovarian cancer." (PMID 36176400, 2022). "Specific CpG sites identified here have been found to be associated with lung cancer (cg05951221 and cg21566642 of 2q37.1, cg05575921 of AHRR, cg03636183 of F2RL3), atherosclerosis (cg05575921 of AHRR), body mass index (cg23576855 of AHRR, cg09554443 of CD247), and mortality (cg05575921 of AHRR)." (PMID 29047347, 2017).
lymphoma (3 papers, 2019 to 2025). A malignant (clonal) proliferation of B- lymphocytes or T- lymphocytes which involves the lymph nodes, bone marrow and/or extranodal sites. "However, investigations regarding the involvement of CD247 in the other two lymphomas have not been conducted thus far." (PMID 40360443, 2025).
combined immunodeficiency (2 papers, 2025). A broad classification of inherited disorders presenting at birth that affect both the cell-mediated and humoral aspects of the immune response. "For the study of the impact of CD247 variants on surface TCR expression and function, we selected the variants reported in a 10-month-old child with severe combined Immunodeficiency (SCID) caused by CD247 deficiency." (PMID 40711587, 2025).
thymoma (2 papers, 2021 to 2022). A neoplasm arising from the epithelial cells of the thymus. "In 2018, his team further suggested that deficient CD247 expression was a typical histopathological characteristic of thymomas with cortical features." (PMID 35774508, 2022). "The low expression of CD247 and the decrease in the number of mature T-cells are the common features of thymomas and these three PNS." (PMID 35774508, 2022). "In summary, the common characteristics of thymomas and these three PNS are the low expression of CD247 and the inhibition of T-cell differentiation." (PMID 35774508, 2022).
acute myocardial infarction (1 paper, 2024). Necrosis of the myocardium, as a result of interruption of the blood supply to the area. "Similar to CD48, CD247 and Acute Myocardial Infarction (AMI) have not been conclusively linked by research." (PMID 38783198, 2024).
Behcet disease (1 paper, 2025). A chronic, relapsing, multisystemic vasculitis characterized by mucocutaneous lesions, as well as articular, vascular, ocular and central nervous system manifestations. "Furthermore, through multiomics data analysis and machine learning techniques, researchers identified CD247, CD2, and CCR7 as diagnostic biomarkers for AAA in Behcet's disease patients and developed a nomogram model for diagnosis." (PMID 40995065, 2025).
Cirrhosis (1 paper, 2023). A chronic disorder of the liver in which liver tissue becomes scarred and is partially replaced by regenerative nodules and fibrotic tissue resulting in loss of liver function. "Therefore, we suggest that CD8A and CD247 may promote the progression of cirrhosis to HCC by mediating the chronic inflammatory response." (PMID 37461343, 2023).
colorectal cancer (1 paper, 2017). A primary or metastatic malignant neoplasm that affects the colon or rectum. "In colorectal cancer tissue, tumour CD247 (PD-L1) is inversely associated with FoxP3+, but not CD3+, CD8+ or CD45RO+ cell density." (PMID 29245908, 2017).
depression (1 paper, 2022). "Furthermore, we discovered other target genes and drug repurposing candidates for depression, the efficacies of which are supported by published evidence; for example, muromanab, which targets CD3D/CD247, and taurine, which targets GABBR1." (PMID 36009493, 2022).
epilepsy (1 paper, 2021). A brain disorder characterized by episodes of abnormally increased neuronal discharge resulting in transient episodes of sensory or motor neurological dysfunction, or psychic dysfunction. "The PPI showed that there are six resistance genes (CD247, CTSW, IL2RB, MATK, NKG7, and PRF1) that may play a central role in the resistance of epilepsy patients." (PMID 34805265, 2021).
follicular lymphoma (1 paper, 2025). Follicular lymphoma is a form of non-Hodgkin lymphoma characterized by a proliferation of B cells whose nodular structure of follicular architecture is preserved. "Our findings revealed a robust association between CD247 and Hodgkin lymphoma, non‐follicular lymphoma, DLBCL, as well as mature T/NK cell lymphomas." (PMID 40360443, 2025). "Consequently, our findings suggest that CD247 may also influence Hodgkin lymphoma and non‐follicular lymphoma." (PMID 40360443, 2025).
glioblastoma (1 paper, 2024). The most malignant astrocytic tumor (WHO grade IV). "Our investigation revealed that glioblastomas with high RCD.GP scores highly expressed immune checkpoint genes, including CD274, CD247 and so on." (PMID 38378721, 2024).
glioma (1 paper, 2024). A benign or malignant brain and spinal cord tumor that arises from glial cells (astrocytes, oligodendrocytes, ependymal cells). "The immune clusters with multitumor contributions corresponded to macrophages (C3, MSR1) and T cells (C21, CD247, and TRAC), while C31 cells were microglia of glioma with multipatient contributions, and C41 cells were Kupffer cells of ICC with multipatient contributions." (PMID 38010945, 2024).
Hodgkins lymphoma (1 paper, 2025). A heterogeneous group of malignant lymphoid neoplasms of B-cell origin characterized histologically by the presence of Hodgkin and Reed-Sternberg (HRS) cells in the vast majority of cases. "Our findings exhibited significant correlations in Hodgkin's lymphoma between CD247, CMTM6, CD25, ENTPD1, MBL2, and CD40." (PMID 40360443, 2025).
influenza (1 paper, 2014). An acute viral infection of the respiratory tract, occurring in isolated cases, in epidemics, or in pandemics; it is caused by serologically different strains of viruses (influenzaviruses) designated A, B, and C, has a 3-day incubation period, and usually lasts for 3 to 10 days. "NK cell response related genes such as CD247, KIR2DL4, KIR3DL1, KIR3DL3 and KLRB1 were down-regulated only in moderate and severe patients while genes such as KIR2DL1, KIR2DS4 and KIR3DL2 were down-regulated in all three groups of influenza patients." (PMID 25365328, 2014).
kidney damage (1 paper, 2025). "CD247 was also one of the most influential ITC for AA, and the potential linkage between kidney damage and AA in patients with immune problems have been reported previously, which suggests that CD247 could be the key to tackle both cases." (PMID 39897058, 2025).
Mycobacterium infection (1 paper, 2021). Infections with bacteria of the genus Mycobacterium. "The role of the remaining 7 genes (CD2, CD6, CD247, ZAP70, CD3D, SH2D1A, and CD3E) in T-cell signaling and modulation of host immune responses in mycobacterium infections is also supported." (PMID 35198572, 2021).
neuroblastoma (1 paper, 2024). Neuroblastoma (NB) is the most common solid, extracranial childhood tumor. "We analyzed the expression of endothelial markers (EGFL7, FLT1, PTPRB33), mesenchymal cells (COL1A2, COL1A1, PDGFRB34,35) and immune markers (ITGAM, CD247, PTPRC36–38) in MYCN-amplified neuroblastoma patient samples (with at least 90% tumor purity) and tumors from Protocol #4." (PMID 39367051, 2024).
Obesity (1 paper, 2021). Accumulation of substantial excess body fat. "CD247 is known to regulate blood pressure, which is a critically affected factor in the case of T2D and obesity, by altering T-cell infiltration in the kidney; it also has an important impact on other human diseases." (PMID 33927693, 2021).
preeclampsia (1 paper, 2017). Preeclampsia is a hypertensive disorder of pregnancy that is characterized by new-onset hypertension with proteinuria presenting after 20 weeks of gestation, and depending on mild or severe forms may initially present with severe headache, visual disturbances, and hyperreflexia. "However, genes like HSP90, PAK2, CD247 and others included in the first 1% of the prioritized list need to be further explored in preeclampsia pathogenesis through experimental approaches." (PMID 28789679, 2017). "However, other genes like HSP90, PAK2, CD247 and others included in the first 1% of the prioritized list need to be further explored in preeclampsia pathogenesis through experimental approaches." (PMID 28789679, 2017).
rectal cancer (1 paper, 2024). A primary or metastatic malignant neoplasm that affects the rectum. "CXCL10, IL12A, CD247 and ITGB1 were identified as predictive markers for the response to neoadjuvant treatment in rectal cancer in previous studies." (PMID 38406803, 2024).
schizophrenia (1 paper, 2012). A major psychotic disorder characterized by abnormalities in the perception or expression of reality. "Besides categories related to hematological function, the Tan schizophrenia module was also enriched for the Neurological Disease category (CCL5, PRKCQ, PTAFR, AKR1B1, CD247, IL10RA and KHSRP)." (PMID 22761806, 2012).
Sjogren syndrome (1 paper, 2024). An autoimmune disorder in which immune cells attack and destroy the glands that produce tears and saliva. "Lastly, rs2949661 is also shown to be associated with Sjogren’s syndrome by being an eQTL to both genes CD247 and cellular repressor CREG1 and by altering TAD interactions involving CD24784." (PMID 39289357, 2024).
systemic inflammatory response syndrome (1 paper, 2024). SIRS is a serious condition related to systemic inflammation, organ dysfunction, and organ failure. "The results of a meta-analysis suggested that FYN could contribute to patient prognosis and that CD247 could be used to distinguish between patients with sepsis and patients with systemic inflammatory response syndrome (SIRS)." (PMID 38716051, 2024).
T/NK cell lymphomas (1 paper, 2025). "In mature T/NK cell lymphomas, a significant association was observed between CD247 and ENTPD1." (PMID 40360443, 2025).
triple-negative breast carcinoma (1 paper, 2025). An invasive breast carcinoma which is negative for expression of estrogen receptor (ER), progesterone receptor (PR), and human epidermal growth factor receptor 2 (HER2). "For instance, in triple-negative breast cancer (TNBC), patients with low expression of the CD247 and CD4 gene phenotypes tend to have poorer outcomes." (PMID 40710213, 2025).
type 2 diabetes mellitus (1 paper, 2023). A type of diabetes mellitus that is characterized by insulin resistance or desensitization and increased blood glucose levels. "DNA replication, fatty acid elongation, mismatch repair, and protein export were significantly enriched in the high CD247 subgroup, but arachidonic acid metabolism and type II diabetes mellitus were significantly enriched in the low CD247 subgroup." (PMID 37950194, 2023).
viral infection (1 paper, 2013). "The transient down-regulation of CD247 occurs after time-limited exposure to antigen, such as during an acute viral infection." (PMID 23977094, 2013).
tumor (52 papers, 2008 to 2025). "Furthermore, we also found that a low expression of CD247 might be associated with a lower activity of TIL (tumor-infiltrating lymphocytes), checkpoint, and cytolytic activity and a higher activity of macrophages and neutrophils." (PMID 34880861, 2021). "Three tumor antigens, such as CD247, FCGR1A, and Trap, have been identified in CCA and are associated with a good prognosis and antigen-presenting cell infiltration." (PMID 37138880, 2023). "In this study, we developed PAR1-targeted CAR-T cells using third-generation CARs containing additional signaling domains, including CD28, CD137 (4-1BB), and CD3ζ (CD247), to augment activation of cytokine production and a tumor-eradication ability." (PMID 37667257, 2023). "Some data have shown that immunosuppression of the tumor microenvironment is related to the downregulation of CD247." (PMID 37461343, 2023). "Immunohistochemical staining was performed on tumor tissues from 80 patients, and the expression of CD247 was scored based on staining intensity." (PMID 37955651, 2023). "Compared with the normal tissues, FN1, IL10, and MYC were highly expressed, while the expression of CD247 was decreased in tumor bladder tissues." (PMID 36389789, 2022). "The elevated expression of CD247, FCGR1A and TRRAP were associated with superior OS and RFS of CHOL, indicating that the three tumor antigens have potential immune-stimulatory effects." (PMID 33685460, 2021). "Three tumor antigens (CD247, FCGR1A, and TRRAP) correlated with superior prognoses and infiltration of antigen-presenting cells in CHOL were identified using narrow-down analysis, thus promising candidates for mRNA vaccine." (PMID 33685460, 2021). "Looking at all studies across all tumor entities, patients whose tumors express CD247 appear to respond better to PDCD1 blockade than patients without CD247 expression." (PMID 33240813, 2020). "T cells were engineered to have the ability to attack tumor cells by generating CAR constructs consisting of genes encoding scFv, a co-stimulatory domain (CD28 or TNFRSF9), and CD247 signaling domains for T cell proliferation and activation." (PMID 32050611, 2020). "The PDCD1/CD247 axis plays a pivotal role in the effector function of T-cells, i.e., in T-cells residing within (tumor) tissue." (PMID 33240813, 2020). "In contrast, the expressions of RAC2 (p = 0.0405), ZAP70 (p = 0.0121), IL2RG (p = 0.0175) and CD247 (p = 0.0112) were downregulated in tumour tissues." (PMID 29967488, 2018). "Meanwhile, the immune analysis results indicate that high expression of CD247 may enhance T-cell mediated anti-tumor immunity by regulating the immune infiltration of CD8 + T cells." (PMID 41488073, 2025). "The heatmap showed significant differential expression of genes such as HSPA9, CCL19, and CD247 in cluster B, which may implicate their roles in tumor progression." (PMID 38312844, 2024). "The upregulation of TLR2 and CD247 in current work was significantly associated with the superior prognosis, suggesting that TLR2 and CD247 activation may be essential for anti-tumor immunity." (PMID 36389789, 2022). "Therefore, high expression of CD247 may enhance T-cell-mediated anti-tumor immunity by actively regulating immune infiltration of CD8 + T cells." (PMID 41488073, 2025). "Although no direct studies have been conducted to investigate the impact of CD247 splicing variations on tumor immunity, we may assume that they may indirectly affect tumor immune responses because of their significant influence on T cell development and activation." (PMID 40032844, 2025). "CD247 may induce tumor cell apoptosis and cell cycle arrest by affecting immune cell infiltration." (PMID 41488073, 2025). "Additionally, we performed correlation analysis to corroborate the relationship between tumor infiltrated immune cells and the expression of the seven key hub genes (CTLA4, PRF1, LCK, CD3E, CD247, ZAP70, and LCP2) in ARID1A-PIK3CA mutational co-occurrence tumors." (PMID 38017109, 2023).